RNU4-88P (RNA, U4 small nuclear 88, pseudogene)
Gene: Small nuclear RNA gene on chromosome 1 (66,094,461 to 66,094,546, reverse strand). Ensembl gene ENSG00000223152.
Homologues: Orthologues: macaque U4 (94% identical), dog U4 (74% identical), tropical clawed frog U4 (71% identical), tropical clawed frog U4 (70% identical), tropical clawed frog U4 (65% identical), tropical clawed frog U4 (64% identical), tropical clawed frog U4 (63% identical). Paralogues in human: RNU4-39P (79% identical), RNU4-33P (77% identical), RNU4-36P (77% identical), RNU4-55P (77% identical), RNU4-59P (77% identical), RNU4-67P (76% identical), RNU4-72P (76% identical), RNU4-9P (76% identical), RNU4-49P (74% identical), RNU4-82P (74% identical), RNU4-87P (74% identical), RNU4-91P (74% identical), and 80 more.